HIF1A (hypoxia inducible factor 1 subunit alpha)
Diseases named in the same sentence as HIF1A in open-access papers (continued):
Sharing a sentence is not in itself a finding about the gene and the disease.
glioma (continued). "Notably, Pearson’s correlation analysis also showed a positive correlation between HIF-1α and MCT4 expression levels in the gene expression dataset of patients with glioma." (PMID 32045997, 2020). "Furthermore, we demonstrated that celastrol reduced HIF-1α expression, and the phosphorylation of PI3K, Akt, and mTOR in U87 orthotopic glioma xenografts." (PMID 32116702, 2020). "Specimens from seven glioma cases were analyzed by immunohistochemical staining for CD34, lymphatic endothelial hyaluronic acid receptor 1 (LYVE‐1), prospero‐related homeobox 1 (Prox1), nestin, and hypoxia‐inducible factor 1α (HIF‐1α)." (PMID 31960509, 2020). "On the other hand, HIF1α has been reported to directly upregulate BMP4 expression in various types of cells and indirectly stabilize NOTCH1 protein and activate NOTCH1-HES1 signaling in human glioma stem-like cells and T lymphocytes." (PMID 33015064, 2020). "IGFBP2 has been reported to exert an oncogenic effect by enhancing invasiveness, angiogenesis, and VM formation and as part of a negative feedback loop with HIF1α in glioma." (PMID 32765489, 2020). "Next, we overexpressed HIF-1α in U-87MG and U-138MG cells to verify whether HIF-1α is involved in ELTD1-regulated glioma cell proliferation." (PMID 31554859, 2019). "HIF1α activates target gene expression involved in vascularization, glucose transport, energy metabolism, and growth and metastasis, including VEGF, PDK1, Cyclin-D2, and CA9, and makes glioma cells adapt to hypoxic environments." (PMID 30082910, 2019). "In addition, ANKDD1A also decreased the half-life of HIF1α by upregulating FIH1, decreased glucose uptake and lactate production, inhibited glioma cell autophagy, and induced apoptosis in GBM cells under hypoxia." (PMID 30082910, 2019). "In our study, we confirm that miR-9 can directly bind to the 3’-UTR of COL18A1, THBS2, PTCH1 and PHD3, promote the degradation of these mRNAs and initiate HIF-1α/VEGF signal transduction, thus markedly enhancing tumorigenesis and angiogenesis during the glioma progression." (PMID 30795814, 2019). "Given the characteristic hypoxic microenvironment of glioma, we initially assessed whether STAT6 is related to HIF-1α expression, since HIF-1α is the critical mediator to hypoxic adaptation and survival." (PMID 31530290, 2019). "Interestingly, HIF-1α, Snail, Twist and p-ERK expression was more downregulated in shPLOD3 glioma cells compared with shLuc control cells under hypoxic conditions than under normoxic conditions." (PMID 29644003, 2018). "However, we observed a significant increase of HIF1A and PDL1 in mRNA and protein levels in all glioma cell lines after treatment with MLN4924." (PMID 30393513, 2018). "Among the targets of HIF1α is the lncRNA H19, an imprinted non coding RNA which expression was found up-regulated in many tumours including CRC, hepatocellular carcinoma, testicular cancer, choriocarcinoma, osteosarcoma, esophageal cancer and glioma." (PMID 28061476, 2017). "pAKT and HIF-1α are involved in the PI3K pathway, and we provided evidence that these proteins were upregulated in both overexpression of miR-218 and knockdown of Bmi1 glioma cell lines." (PMID 29220380, 2017). "Although the detailed molecular interactions remains unclear, It is not hard to find the pivotal role of hypoxia inducible factors, HIF-1α and HIF-2α in glioma radioresistance." (PMID 29246031, 2017). "The IRS of HIF-1α in the tumour did not correlate with the SUVtumor of 18F-FMISO in either newly diagnosed or recurrent glioma." (PMID 29212283, 2017). "FoxO3 transcriptional activity attenuates ROS levels, reducing HIF-1α stabilization in normal cells, however as FoxO3 activity is often downregulated due to oncogenic signaling, HIF-1 is further stabilized by increased ROS tolerance in glioma." (PMID 28491867, 2017). "Both HIF-1α and HIF-2α have been found to regulate Notch signaling in glioma stem cells." (PMID 29238372, 2017).
glioma (continued). "Moreover, we have shown that PLOD2 is induced by HIF-1α and then mediates hypoxia-induced EMT and migration in glioma cells." (PMID 28410212, 2017). "Similar to the results of TFF3 expression in different grade glioma samples, higher HIF-1α expression was found in high-grade (WHO grades III and IV) than low-grade (WHO grades I and II) glioma tissues, showing a statistically significant difference between these groups (P<0.001)." (PMID 29100347, 2017). "After verifying the correlation of HIF1α and MIF with CXCR4 in gliomas, we further explored whether hypoxia-induced high co-expression of MIF and CXCR4 was correlated with the formation of VMs." (PMID 29113309, 2017). "As a corollary, although the mechanism of TFF3-HIF-1α interaction needs further investigation, inhibition of TFF3 might offer a novel strategy to target HIF-1α and retard glioma progression." (PMID 29100347, 2017). "Parallel with HIF-1α, the expression of TFF3 was correlated with the WHO grade of gliomas." (PMID 29100347, 2017). "Since TFF3 was cooperated with HIF-1α to promote the tumorigenesis of glioma, we tried to investigate whether TFF3 regulates the expression of HIF-1α, Western blotting analysis was performed." (PMID 29100347, 2017). "ACF had no direct effect on the expression of HIF-1α in either glioma cells or HMDMs, a finding that is in agreement with the results described in other reports." (PMID 27602954, 2016). "HiF-1α was localized to the nuclei in high-grade gliomas, but it was primarily cytosolic in low-grade gliomas and normal human astrocytes." (PMID 26689994, 2016). "Gliomas develop within a mechanically challenged microenvironment that is characterized by a dense extracellular matrix (ECM) that compromises vascular integrity to induce hypoxia and activate HIF1α." (PMID 27820599, 2016). "Finally, levels of GFAP and HiF-1α are highly correlated, generating a R2 value of 0.48 (p = 0.0006) in GBM and 0.35 (p = 0.0053) in all glioma." (PMID 26689994, 2016). "We also compared the cross-correlation of MAOB, HiF-1α and GFAP levels among all the gliomas." (PMID 26689994, 2016). "Compared to HIF-1α, which is expressed both in glioma/glioblastoma CSCs and non-stem cancer cells in hypoxia, HIF-2α has a unique expression pattern – it is highly induced only in CSCs." (PMID 26210994, 2015). "Further analyses correlated the high expression of MGMT with the presence of a hypovascular central core of the tumor, where activation of the hypoxia inducible factor (HIF)-1α will in turn promote expression of MGMT, particularly in the hypoxic glioma stem cells niches." (PMID 26035292, 2015). "In addition to HIF-1α and VEGF, which contribute to the mechanisms of VM formation, another known factor that promotes the VM formation of highly malignant glioma cells is the hypoxic condition." (PMID 25667663, 2015). "The consistency between the lower expression of miR224-3p and the higher expression of HIF1α and LC3B in glioma tissue in part validates the hypothesis." (PMID 26536662, 2015). "HIF-2α, but not HIF-1α, is induced under hypoxic conditions and upregulation of this factor is critical to maintaining the tumorigenicity of glioma stem cells." (PMID 25749383, 2015). "By contrast, transient expression of HIF1α(PP) in U-87 MG cells or constitutive expression of HIF1α(PP) but not HIF2α(PP) in a patient-derived glioma sphere culture inhibited tumor growth and spread." (PMID 25893706, 2015). "In order to examine the effect of nuclear accumulation of HIF-1α in the radiation resistance of glioma cells following transient reoxygenation in vitro, U87 cells were transfected with either a HIF-1α-expressing construct (HA-HIF1α-pcDNA3) or an empty vector (pcDNA3)." (PMID 25350400, 2014). "Consistent with previous studies, Egln3H196A was expressed at levels comparable to wild-type Egln3 in Hu-glioma cells in vitro and did not promote the degradation of Hif-1α or Hif-2α." (PMID 22905089, 2012).
glioma (continued). "Similarly, for Rt-glioma cells infected with a Dox-inducible Egln3 construct, the presence of 1μg/mL Dox (6hrs) up-regulated the expression of Egln3 protein and caused ≈50% decreases in Hif-2α protein levels after a 6hr exposure to hypoxic conditions without significantly altering Hif-1α expression." (PMID 22905089, 2012). "In summary, these results suggest that 3-hydroxybutyrate does not modulate HIF-1α expression or activity in the glioma cell lines analyzed, and therefore provide additional evidence for a defective ketone body utilization of glioma cells." (PMID 21791085, 2011). "Previous reports have indicated key roles for HIF1A and STAT3 in glioblastoma aggressiveness, confirming the validity of this rank-order approach for identifying upstream transcription factors regulating the invasive phenotype of human gliomas." (PMID 20565806, 2010). "In concordance with our results, glioma cells knocked down for HIF-1α using an siRNA approach failed to invade the surrounding brain tissue, as assessed using an organotypic brain slice model." (PMID 20515450, 2010). "Notably, the correlation between PAX6 and HIF-1α has not been previously reported, and our findings suggest a potential negative regulatory relationship between these two factors in gliomas." (PMID 41154694, 2025). "However, limitations persist, as we have not completely clarified the mechanisms by which PAX6 regulates HIF-1α nor have we fully explored the specific interactions between oxidative stress and iron metabolism in gliomas, which requires further investigation." (PMID 41154694, 2025). "Moreover, sublethal PDT induces an increase in the HIF-1α expression in healthy brain tissue as well, stimulating the expression of the ADAM17–EGFR–PI3K–Akt pathway and increasing the invasion of subsequently implanted glioma cells." (PMID 39201395, 2024). "In agreement with our results showing that BCP downregulates VEGF release and HIF-1α expression in lung cancer cells under hypoxic conditions, the same group had demonstrated by cDNA array analysis that JWH-133 reduces the mRNA of these angiogenesis factors in experimental gliomas." (PMID 38255884, 2024). "The activation of HIF-1α expression or activity by PLD2 has been reported in endothelial, glioma and renal cancer cells, but there is evidence of the opposite effect in HEK293 cells, suggesting that this feedback loop may work in specific contexts or cell types." (PMID 38403587, 2024). "Interestingly, low oxygen level induced increased IFITM3 and HIF1α expression in GSCs, rather than glioma cell lines." (PMID 38218875, 2024). "To confirm the clinical significance of LINC02774 and examine whether the downstream targets of LINC02774 exhibit consistent changes in clinical glioma specimens, we analyzed the expression levels of LINC02774, PHD3, RP58, HIF‐1α, VEGF, and GLUT1 in different grades of glioma tissues." (PMID 37701531, 2023). "In addition, strong expression of Ki-67, partial expression of EGFR and VEGF, and weak expression of MGMT and HIF-1α was oberserved on immunohistochemical staining, These supplementary characteristics will make GSC glioma model a better test platform for glioma." (PMID 36591483, 2022). "According to our results, despite of the roles of miR-210-3p on mitochondrial functions, HIF-1α induced miR-210-3p may also promote malignant behaviors, including invasiveness and EMT in glioma cells, which may also be involved in the regulation of mitochondrial function." (PMID 34197482, 2021). "However, more experiments, like knockdown or inhibition of Akt or HIF-1α in Cav-1-overexpressing glioma cells and protein-protein interactions in hypoxic conditions, need to be done to evaluate the direct role of Akt and HIF-1α in glioma VM formation." (PMID 34287575, 2021). "In glioma, whether miR-495-3p regulates the expression of HIF1A and MMP14 or the formation of VM has not been reported." (PMID 34345216, 2021).
glioma (continued). "Therefore, in this study, we examined the correlation between the expression of the BMAL1 gene and the expression of HIF-1a, ANG1, ANG2, and VEGF in human glioma tissues, as well as the relationships between the expression of the BMAL1 gene and the number of tumor microvessels and peritumor edema." (PMID 34815366, 2021). "In addition to GBM, co-expression of HIF1α and PDGFRα proteins was also observed in other types of gliomas, but not in medulloblastoma or adjacent normal brain tissues (ANB)." (PMID 34470658, 2021). "The abundance of exhausted T cells and B cells was significantly higher in the high-HIF1A-expression group, while that of macrophage, monocyte, and natural killer cell was significantly higher in the low-HIF1A-expression group in both GBM and lower-grade glioma." (PMID 34305618, 2021). "Moreover, expression of HIF-1α, and its downstream target genes vascular endothelial growth factor (VEGF), glucose transporter (GLUT1), and carbonic anhydrase (CA9), show increased expression in higher grade gliomas compared to lower grade." (PMID 33842321, 2021). "To more directly assess the impact of BMAL1 on the expression levels of HIF-1a, ANG2 and VEGF we used primary glioma cells to construct cell models with BMAL1 overexpression and silencing and to determine whether BMAL1 is involved in HIF-1a, ANG2 and VEGF expression in gliomas." (PMID 34815366, 2021). "However, other researchers also have reported that miR-26a could upregulate the expression of HIF-1α, VEGF, and Ang1 to enhance the angiogenesis in glioma and bone defect." (PMID 31730486, 2019). "Interestingly, our results reveal that PLOD2 is directly induced by HIF-1α through the HREs located within the PLOD2 promoter and therefore may mediate hypoxia-induced EMT in glioma cells." (PMID 28410212, 2017). "Notably, overexpression of HIF-2α in non-GSCs transformed them into GSCs, and HIF-2α, but not HIF-1α, expression correlated with survival in high-grade glioma patients." (PMID 29246031, 2017). "Moreover, PLOD2 could be induced by hypoxia-inducible factor-1α (HIF-1α) via hypoxia, thereby promoting hypoxia-induced EMT in glioma cells." (PMID 28410212, 2017). "Similarly, TMZ therapy significantly increased the rate of single-cell conversions, and therapy-induced HIF1a and HIF2a seem to play key roles in allowing non-stem glioma cells to acquire stem-like traits." (PMID 29296224, 2017). "However, the distribution of these two molecules was not significantly altered in low and high HIF-1α expressing gliomas." (PMID 27602954, 2016). "However, an increase in the production of POSTN and a more diffuse distribution of POSTN were observed in both perivascular and non-vascular areas in the high HIF-1α expressing glioma specimens." (PMID 27602954, 2016). "HIF-1α/2α were proven to be differently regulated in a number of tumors and seem to have a different impact on tumor behavior and patient outcome in neuroblastoma, glioma/glioblastoma as well as breast and non-small cell lung carcinoma." (PMID 26210994, 2015). "In addition, some authors, with a proteomic approach, support the possibility that this dipeptide affects tumour cell growth in the human glioma cells and retards tumour growth in vivo in a NIH3T3-HER2/neu mouse model through an interference with protein folding/processing and HIF-1α signalling." (PMID 24804733, 2014). "The mechanisms of the ATRA-induced HIF-1α expression in glioma cells are still not entirely clear." (PMID 23554794, 2013). "In addition to upregulating the expression of HIF-1α, ATRA may also act through some other pathways to regulate VEGF expression in glioma cells." (PMID 23554794, 2013). "However, no activation of the hypoxia-inducible factor-1α (HIF-1α) pathway was observed in glioma cells, consistent with the absence of substantial 3-hydroxybutyrate metabolism and subsequent accumulation of succinate." (PMID 21791085, 2011).
glioma (continued). "Presented results indicate that deletion of STAT3 has a significantly suppressive effect on expresison of examined glioma and hypoxia related markers in vitro which could be recapitulated in vivo where, however, this effect is not universal as seen in case of HIF1a and VEGFC expressions." (PMID 38654280, 2024). "In addition to hypoxic conditions, HIF-1α can also be induced by various chemical compounds such as pravastatin, deferoxamine (DFO), and cobalt chloride in miscellaneous brain cells including endothelial cells, glioma cells, and neurons under normoxic conditions." (PMID 39594520, 2024). "Furthermore, HIF-1α stabilization also upregulates GLUT1 and GLUT3 transporter expression and phosphofructokinase (PFK1) expression, allowing for elevated glucose uptake, increased glycolytic capacity, and rapid production of the ATP needed to sustain the high metabolic demand of glioma cells." (PMID 38026690, 2023). "Notably, many Prox1+ HIF‐1α+ cells were distributed in gliomas but not seen in normal brain tissue." (PMID 31960509, 2020). "However, the regulation between TFF3 and HIF-1α has not yet been elucidated in glioma." (PMID 29100347, 2017). "Hyperbaric oxygen therapy (HBOT) could inhibit glioma cell proliferation and inflammatory cell infiltration, and exert a sensitizing effect on ACNU therapy partially through enhancing oxygen pressure (PO2) in tumor tissues and lower expression levels of HIF‐1α, TNF‐α, IL‐1β, VEGF, MMP9, and NF‐κB." (PMID 27734611, 2016). "In addition, several lines of evidence suggest that HIFs promote the expansion of CD133-positive glioma cells or expression of CD133 in lung cancer cells; however, how the expression of the CSC marker protein is regulated by HIF-1α and HIF-2α remains largely unknown." (PMID 23840432, 2013). "To determine whether suppression of p70S6K1 expression due to miR-128 overexpression affects HIF-1 expression in glioma, we found that HIF-1α but not HIF-1β protein levels were inhibited in U87 and U251 cells stably expressing miR-128 when compared to cells stably expressing miR-SCR." (PMID 22442669, 2012). "Additionally, it has been shown that FTL knockdown inhibits glioma cell proliferation and increases apoptosis in cells treated with TMZ, suggesting that FTL may contribute to TMZ resistance in glioma, and its regulation by HIF-1α represents a potential therapeutic target." (PMID 41155273, 2025). "This demonstrated a significant overexpression of MYBL2, FOXM1, ETS1, HIF-1A, and JUN in both glioma cohorts compared to non-neoplastic brain tissues." (PMID 35228525, 2022). "Although Glut1- and Hif1a-KD IG27 gliomas showed significantly reduced PS and increased PVS, with Glut1-KD IG27 glioma exhibiting PVS but not PS clearly." (PMID 33506198, 2021). "The results showed that under hypoxia(24 h), the expression of HIF-1α increased dramatically, but NKILA did not change significantly in glioma cells." (PMID 32382013, 2020). "The results showed that there was a significant accumulation of HIF-1α protein in the cells, but the expression of NKILA was not upregulated in glioma." (PMID 32382013, 2020). "Hypoxia affected glioma cell lines differently from adenocarcinoma cell lines: 8 proteins were increased in gliomas (BAX, caspase 7, HIF-1α, c-JUN, MEK1, PARP 1 cleaved, Src, and VEGFR2) and none in adenocarcinomas." (PMID 22276931, 2012). "Notably, while confirming that the HIF-1α inhibitor YC-1 has no significant cytotoxicity on glioma cells, we have noticed that YC-1 downregulates the expression of LAMC1 while inhibiting HIF-1α expression at the same time." (PMID 38678297, 2024). "In addition, our data confirm that there are positive correlations among FBXO22, HIF-1α, and VEGFA expression, and there is a negative correlation between FBXO22 and VHL protein expression in glioma patients." (PMID 38519492, 2024).